KRAS (KRas proto-oncogene, GTPase)
Diseases named in the same sentence as KRAS in open-access papers (continued):
Sharing a sentence is not in itself a finding about the gene and the disease.
astrocytoma (11 papers, 2014 to 2025). "In both groups, GSVA showed that astrocytoma was associated with hallmark gene sets, such as KRAS signaling, fatty acid metabolism, and hypoxia, and oligodendroglioma was associated with the EMT, DDR, TGF-β, and TNF-α pathways." (PMID 35287567, 2022). "Some pediatric astrocytomas lacking the BRAF V600E mutation contain KRAS or other mutations in pathways that increase BRAF activity." (PMID 25563358, 2014). "Previous work describes a genetically engineered mouse (GEM) model that contains perturbations in the most frequently dysregulated networks in GBM (driven by RB, KRAS and/or PI3K signaling and PTEN) that induce development of Grade IV astrocytoma with properties of the human disease." (PMID 25431423, 2015).
cervical adenocarcinoma (11 papers, 2015 to 2026). An adenocarcinoma arising from the cervical epithelium. "KRAS mutations are detected in 0%–1.3% of cervical squamous cell carcinoma and in 8.3%–17.5% of cervical adenocarcinoma." (PMID 36691316, 2023). "KRAS proto-oncogene, GTPase (KRAS) is an oncogene in which mutations are found in 8–23% in cervical adenocarcinomas but rarely in cervical squamous cell carcinomas." (PMID 28771191, 2017). "However, it was reported that KRAS mutations were rarely found in CSCC but were frequently observed in cervical adenocarcinomas, indicating that KRAS mutations in CSCC were uncommon." (PMID 35422066, 2022). "KRAS mutations were detected in 16.7% of cases, consistent with the literature reporting KRAS as a recurrent alteration in 10–20% of cervical adenocarcinomas, particularly in HPV-negative and gastric-type tumors." (PMID 41597409, 2026). "Except for PIK3CA and KRAS, the four other genes were identified as novel driver genes in cervical adenocarcinoma, which might need further validation." (PMID 33398034, 2021). "Fourth, in our study, after the evaluation of WES data in 20 cervical adenocarcinomas, six genes (i.e., PIK3CA, KRAS, TRAPPC12, NDN, GOLGA6L4, and BAIAP3) were predicted as driver genes that could promote tumor formation and development." (PMID 33398034, 2021).
Insulin resistance (11 papers, 2017 to 2026). Increased resistance towards insulin, that is, diminished effectiveness of insulin in reducing blood glucose levels. "Several experiences highlighted that, in addition to KRAS mutations, other factors, like changes in the tumor microenvironment (TME) supported by chronic inflammation, insulin resistance, a fatty diet, or factors associated with obesity, may increase KRAS activation and metabolic reprogramming." (PMID 40860798, 2025). "But in general, circulating biomarkers of insulin resistance and adipokines were at most weakly associated with CRC risk, and not clearly associated with specific subtypes of CRC based on KRAS- and BRAF-mutations and MSI status of the tumor." (PMID 32210264, 2020). "GGPP also activates KRAS/MEK/ERK signaling, which inhibits the insulin signaling pathway PI3K-AKT, leading to insulin resistance." (PMID 40412522, 2025). "The decreased phosphorylation level of JNK suggests that KRAS may inhibit adiponectin expression by regulating JNK and TNF-α, thereby inhibiting adipogenesis under physiological conditions and affecting adipogenesis by regulating insulin resistance." (PMID 34948427, 2021). "Analysis of the target genes revealed that CEBPB, but not KRAS, and SOCS1 was upregulated in obese patients MetS and insulin resistance." (PMID 33540559, 2021).
liver disease (11 papers, 2013 to 2022). "In multivariate analysis, KRAS mutation (HR, 1.495; 95% CI, 1.069–2.092; p = 0.019) and margin status (HR, 1.560; 95% CI, 1.017–3.033; p = 0.043) were significantly correlated with hepatic disease recurrence." (PMID 34440165, 2021). "Out of 20 patients screened at VUmc, 10 were not eligible (60% KRAS mutation, 30% no extra-hepatic disease, 10% declined participation) and the remaining patients were included." (PMID 27196139, 2016). "Strong expression (SE) of KRAS was more frequent in tumors arising from viral (26.8%) than the nonviral group of liver disease (7.7%, p=0.024) and also than cirrhotic parenchyma (0%, p=0.004)." (PMID 33178273, 2020).
mesothelioma (11 papers, 2015 to 2025). A usually malignant and aggressive neoplasm of the mesothelium which is often associated with exposure to asbestos. "Rare cases of mesothelioma have been described with mutations in KRAS, NRAS and potential oncogenic fusions involving ALK and EWSR1 rearrangements, as well as inactivating mutations in VHL raising the possibility of targeted therapy in such cases." (PMID 38015374, 2023). "A recent study indicated that KRAS alterations may promote tumorigenesis in a subset of mesothelioma patients and displayed a repulsive tendency with NF2 mutations." (PMID 40707702, 2025). "We believe that such regimens should also be tested against KRAS-altered mesotheliomas, a molecular subclass we recently identified." (PMID 40707701, 2025). "Notably, NF2 and KRAS are mutually exclusive, indicating that these genes interact to participate in mesothelioma tumorigenesis." (PMID 38879686, 2024).
non-squamous non-small cell lung cancer (11 papers, 2019 to 2025). "Alterations in KRAS account for the most common mutations in non-squamous non-small cell lung cancer (NSCLC)." (PMID 37186063, 2023).
uterine cancer (11 papers, 2011 to 2023). Primary or metastatic malignant neoplasm involving the uterine corpus and/or the cervix. "KRAS is a GTPase that normally functions in growth factor signaling and hypermorphic KRAS mutations occur frequently in various tumor types including colon, lung and uterine cancer." (PMID 24202319, 2013). "The KRAS-variant was found in only 1 of 11 (10%) women younger than 51 years of age at the time of uterine cancer diagnosis, and in 9 of 35 (28%) women who were older, although these prevalence rates were not statistically different (p = 0.41), likely due to small sample size." (PMID 24732316, 2014).
Wilms tumor (11 papers, 2017 to 2025). An embryonal neoplasm characterized by the presence of epithelial, mesenchymal, and blastema components. "Other groups have reported activating mutations of KRAS in human Wilms tumor samples that correlate with hyperactivation of the WNT pathway." (PMID 36612255, 2022). "Our findings indicate that the rs12587 G>T polymorphism in KRAS is associated with increased Wilms tumor susceptibility." (PMID 30860980, 2019). "Our findings indicated that carriers of the KRAS rs12587 GT genotype had a genetic predisposition to Wilms tumor risk." (PMID 30860980, 2019). "False-positive report probability analysis for the association between KRAS genotypes and Wilms tumor susceptibility." (PMID 30860980, 2019). "We further examined the combined effects of the risk genotypes for KRAS on Wilms tumor risk." (PMID 30860980, 2019). "Our study has provided the first evidence that KRAS gene SNPs may increase Wilms tumor susceptibility." (PMID 30860980, 2019). "Stratification analysis for association between KRAS genotypes and Wilms tumor susceptibility." (PMID 30860980, 2019). "They later reported that activating KRAS mutations were found in human Wilms tumor samples." (PMID 30860980, 2019). "KRAS mutant cells secrete prostaglandins to neighboring cells, enhancing the formation and resistance of SGs in KRAS Wilms tumor (WT) cells." (PMID 39253293, 2024). "Of note, copy number gains of KRAS (3 copies) were found in the metastatic Wilms tumor HT120-P0 and corresponding passaged PDXs." (PMID 36612255, 2022). "In conclusion, this was the first multi-center evaluation of the association of KRAS and NRAS gene SNPs with Wilms tumor susceptibility." (PMID 30860980, 2019). "To clarify the association of RAS with Wilms tumor risk, we selected single-nucleotide polymorphisms (SNPs) in the two most common diseased-related RAS genes, KRAS and NRAS, for analysis in a four-center hospital-based case-control study." (PMID 30860980, 2019). "Herein, we evaluated the impact of KRAS and NRAS gene SNPs on the risk of Wilms tumor in 355 Wilms tumor patients and 1070 healthy control subjects." (PMID 30860980, 2019). "Human Wilms’ tumors harboring the KRAS p.Gly12Asp pathogenic variant and not the 14 most common PI3KCA pathogenic variants demonstrated increased pAKT staining on tissue array." (PMID 37154160, 2023). "Compared to individuals without a risk genotype, those harboring one to three KRAS risk genotypes had an adjusted OR of 1.28 for developing Wilms tumor (95% CI=1.002-1.64, P=0.048)." (PMID 30860980, 2019).
acinar cell carcinoma (10 papers, 2014 to 2025). "KRAS mutations are commonly identified in human ductal carcinomas, whereas they are rarely reported in acinar carcinomas, being the latter the most common subtype in dogs." (PMID 38453822, 2024). "At diagnosis, there were 83 (72.8%) stage I/II patients, 76 (66.7%) with acinar adenocarcinoma, and a total of 48 (42.1%) cases and 14 (12.3%) patients with EGFR mutations and other mutations, including KRAS and ALK, respectively." (PMID 32154654, 2020). "Previous studies have indicated that patients with acinar cell carcinoma (ACC) or KRAS wild type (KRASWT) have a higher probability of harboring actionable gene aberrations." (PMID 40314773, 2025). "Multivariable analysis revealed that acinar cell carcinoma (ACC) (Odds ratio [OR] 1.87, 95% confidence interval [CI] 1.00–2.67), KRAS wild type (KRASWT) (OR 3.09, 95% CI 2.49–3.85), and use of F1CDx (OR 2.38, 95% CI 1.98–2.85) were significantly associated with actionable gene aberrations." (PMID 40314773, 2025).
ameloblastoma (10 papers, 2018 to 2025). The most common odontogenic tumor, arising from the epithelial component of the embryonic tooth and usually affecting the molar-ramus region of the mandible or maxilla. "Initially, such mutations have been uncovered in benign epithelial odontogenic tumors wherein BRAF and KRAS mutations were revealed in ameloblastomas and adenomatoid odontogenic tumors, respectively." (PMID 35048058, 2021). "While the BRAF p.V600E mutation emerged as a molecular signature for ameloblastomas and has also been shown to be frequent in other tumors with ameloblastic differentiation, KRAS codon 12 mutations seem to be a marker of adenomatoid odontogenic tumors." (PMID 35048058, 2021). "Notably, B-Raf proto-oncogene serine/threonine kinase (BRAF) and KRAS proto-oncogene GTPase (KRAS) pathogenic mutations have been reported in a high proportion of ameloblastomas and adenomatoid odontogenic tumors, respectively." (PMID 35048058, 2021). "Interestingly, the proportion of AOTs with KRAS driver mutation, is similar to the proportion of driver mutations reported in ameloblastoma." (PMID 35048068, 2021). "It is notable that the KRAS p.G12R mutation, which occurs in adenomatoid odontogenic tumors, has been reported in 4/50 (8%) and 4/28 (14%) of BRAF wild-type ameloblastoma cases." (PMID 35048058, 2021). "In a similar way, other somatic mutations have been reported in ameloblastoma, mainly affecting: SMO, other MAPK pathway-related genes such as KRAS, NRAS, HRAS, FGFR2 and in a lower frequency, PTEN and CTNNB1 among others." (PMID 35048068, 2021). "Mutually exclusive and less common mutations affecting other MAPK-related genes, such as KRAS, NRAS, HRAS, and FGFR2 (a receptor whose stimulation activates MAPK/ERK pathway) have been reported in BRAF wild-type ameloblastomas." (PMID 35048058, 2021). "We found that TLR2, a gene involved in KRAS signaling, was listed as a top‐ranking upregulated gene in the ameloblastoma group." (PMID 32096304, 2020). "In this study, we generated comprehensive gene expression data, which revealed the significant activation of oncogenic gene sets in the ameloblastoma tumor, such as KRAS‐responsive as well as EGFR‐induced genes." (PMID 32096304, 2020). "While there is morphological overlap with AOT and conventional ameloblastoma, it has been shown that AdAM does not exhibit the KRAS and BRAF mutations seen in these two entities, respectively." (PMID 41306250, 2025). "Additional studies showed gene expression profile differences between plexiform and follicular ameloblastomas, with follicular ameloblastomas expressing variants of BRAF, KMT2D, and ABL1, while plexiform ameloblastomas expressed variants of ALK, BRAF, KRAS, KMT2D, SMO, KMT2A, and BRCA2." (PMID 38607614, 2025). "Notably, B‐RAF proto-oncogene serine/threonine kinase (BRAF) and KRAS proto-oncogene GTPase (KRAS) pathogenic mutations have been reported in a high proportion of ameloblastoma and ameloblastoma-related tumors and adenomatoid odontogenic tumors, respectively." (PMID 36378285, 2022). "It is notable that the presence of two or three gene mutations, including somatic mutations in KRAS, PIK3CA, PTEN, FGFR, CDKN2A, and CTNNB1 in the background of either BRAF or SMO mutation-positive ameloblastomas, exclusively occurred in solid/conventional tumors." (PMID 35048058, 2021). "However, somatic KRAS, PIK3CA, PTEN, FGFR, CDKN2A, and CTNNB1 co-occurred also in the background of either BRAF- or SMO-mutated ameloblastomas." (PMID 29388014, 2018). "Additionally, we reported EGFR mutations and the presence of other gene mutations, including somatic mutations in KRAS, PIK3CA, PTEN, FGFR, CDKN2A, and CTNNB1 on the background of either BRAF or SMO mutation-positive ameloblastomas, occurring exclusively in conventional AMs." (PMID 36378285, 2022).
ameloblastoma (continued). "However, other Authors showed additional mutations to B-Raf in ameloblastomas, such as NRAS, HRAS, KRAS, FGFR2, and PIK3CA,10,23,44 suggesting they may represent secondary mutations occurring later in the pathogenesis of ameloblastoma." (PMID 35468886, 2022). "The following sections addressed the main genetic alterations reported for ameloblastomas, mixed odontogenic tumors, odontogenic carcinomas, where BRAF p.V600E mutation is the most important one, and adenomatoid odontogenic tumors which are characterized by KRAS mutations." (PMID 35048058, 2021). "Although use of only single cell line AMU‐AM1, our finding that TLR2 knockdown suppresses KRAS‐related signaling and immune responses in AMU‐AM1 cells strongly indicates the possibility that TLR2 plays a pivotal role in ameloblastoma." (PMID 32096304, 2020).
anaplastic thyroid cancer (10 papers, 2015 to 2025). "One is that certain mutations of the RAS genes, notably HRAS codon 13 mutations previously reported in anaplastic thyroid cancer, and KRAS codon 61 in both PTC and PDTC, were not analyzed." (PMID 32638211, 2021). "In addition, the induction of PTC dedifferentiation into highly aggressive KRAS-driven anaplastic thyroid cancer (ATC) has been reported." (PMID 34638434, 2021).
bone metastasis (10 papers, 2011 to 2026). Transfer of a neoplasm from its primary site to bones. "Nevertheless, additional studies are needed to evaluate the ability of KRAS mutation analysis to risk stratify patients with bone metastasis." (PMID 28051122, 2017). "Various demographic and clinical variables were reported that show inferior prognosis for LUAD with bone metastasis to include: male gender, smoking history, cachexia, malnutrition, poor physical status, multiple and/or wearing bone metastases, KRAS mutation, and without targeted therapy mutations." (PMID 35719977, 2022). "Heterogeneous gene amplification was found both for the ERBB2 and the KRAS genes, but particularly enrichment of ERRB2 amplified cells was found in the biopsy from the bone metastasis after the initial three courses of chemotherapy." (PMID 22014070, 2011).
carcinoid (10 papers, 1998 to 2025). "We report the case of a 71-year-old female in whom three distinct primary lung cancers were identified: carcinoid tumor, adenocarcinoma with KRAS mutation, and adenocarcinoma with EGFR mutation." (PMID 40642683, 2025). "As previously reported 13, 24, we identified sporadic KRAS mutations in both carcinoids and carcinomas." (PMID 27873319, 2017). "Increasing molecular evidence supports the composite lesions hypothesis: shared alterations, such as KRAS, NF1, and BRAF V600E mutations, have been reported in both adenocarcinoma and carcinoid components, suggesting a monoclonal origin in select cases." (PMID 41209982, 2025). "This included HRAS (11p15) amplification on chromothriptic chromosome 11, KRAS (12q12) and ERBB3 (12q13) amplification on chromosome 12, as well as deletions of key carcinoid-associated tumor suppressor genes MEN1 (11q13) and ARID1A (1p36) on chromosomes 11 and 1, respectively." (PMID 39185963, 2025). "No EGFR or KRAS driver mutations were found in carcinoid histology, whereas an enrichment was found for driver mutations in ARID1A." (PMID 38798417, 2024). "None of the BRAF, KRAS, NRAS, or PIK3CA mutations were detected in the carcinoid tumors; moreover, none of the 56 cases exhibited MSI-high status." (PMID 26090613, 2015). "We did not detect KRAS, BRAF, or PIK3CA mutations or MSI-high in the carcinoid tumors." (PMID 26090613, 2015).